H2AC15 (H2A clustered histone 15)
Description:
Core component of nucleosome. Nucleosomes wrap and compact DNA into chromatin, limiting DNA accessibility to the cellular machineries which require DNA as a template. Histones thereby play a central role in transcription regulation, DNA repair, DNA replication and chromosomal stability. DNA accessibility is regulated via a complex set of post-translational modifications of histones, also called histone code, and nucleosome remodeling.
Synonyms: H2A.1; H2AFD; HIST1H2AK; H2A/d
Gene: Protein-coding gene on chromosome 6 (27,835,508 to 27,838,375, reverse strand). Ensembl gene ENSG00000275221.
Subcellular location: Nucleus; Chromosome
Subcellular location (Human Protein Atlas): Nucleoplasm
Pathways (Reactome):
Chromatin organization: HATs acetylate histones; HDACs deacetylate histones; RMTs methylate histone arginines
Disease: Dengue Virus-Host Interactions; HCMV Early Events; HCMV Late Events
Metabolism of proteins: Metalloprotease DUBs; UCH proteinases; Ub-specific processing proteases
Gene Ontology:
Molecular function: enzyme binding; protein binding; structural constituent of chromatin; DNA binding; protein heterodimerization activity
Biological process: chromatin organization; heterochromatin formation
Cellular component: extracellular exosome; nucleoplasm; nucleosome; nucleus; chromosome
Genetic constraint (gnomAD): Loss-of-function variants: 7 observed, 8.12 expected, observed/expected ratio (o/e) 0.86, 90% interval 0.49 to 1.58. That is too few expected variants to judge how well the gene tolerates losing a copy. Missense variants: 234 observed, 186.83 expected, observed/expected ratio (o/e) 1.25, 90% interval 1.12 to 1.4. Synonymous variants: 125 observed, 83.77 expected, observed/expected ratio (o/e) 1.49, 90% interval 1.29 to 1.73.
Homologues: Orthologues: chimpanzee H2AC15 (100% identical), guinea pig H2AC15 (100% identical), macaque H2AC15 (100% identical), Drosophila melanogaster His2A:CG31618 (85% identical), Drosophila melanogaster His2A:CG33808 (85% identical), Drosophila melanogaster His2A:CG33814 (85% identical), Drosophila melanogaster His2A:CG33817 (85% identical), Drosophila melanogaster His2A:CG33820 (85% identical), Drosophila melanogaster His2A:CG33823 (85% identical), Drosophila melanogaster His2A:CG33826 (85% identical), Drosophila melanogaster His2A:CG33829 (85% identical), Drosophila melanogaster His2A:CG33832 (85% identical), and 11 more. Paralogues in human: H2AC11 (100% identical), H2AC13 (100% identical), H2AC16 (100% identical), H2AC17 (100% identical), H2AC7 (99% identical), H2AC12 (98% identical), H2AC18 (98% identical), H2AC19 (98% identical), H2AC4 (98% identical), H2AC6 (98% identical), H2AC8 (98% identical), H2AC14 (98% identical), and 15 more.
Diseases named in the same sentence as H2AC15 in open-access papers:
H2AC15 is named in the same sentence as 2 diseases in open-access papers, as found by Europe PMC text mining. Sharing a sentence is not in itself a finding about the gene and the disease. The quoted sentences say what the papers report.
cancer (1 paper, 2023). A tumor composed of atypical neoplastic, often pleomorphic cells that invade other tissues. "Intriguingly, H3-3A and H1-4 mutations were mutually exclusive across cancers, whereas H2BC8 and H2AC15 significantly co-occurred." (PMID 37640703, 2023).
H2AC15 also shares sentences with these, for which no sentence is quoted: systemic lupus erythematosus (1 paper).